TAAR9 (trace amine associated receptor 9)
Description:
Olfactory receptor specific for trace amines, such as N,N-dimethylcyclohexylamine (DMCHA) and beta-phenylethylamine (beta-PEA) (By similarity). In contrast to mouse and rat orthologs, not activated by triethylamine, cadaverine (CAD) or spermidine. Trace amine compounds are enriched in animal body fluids and act on trace amine-associated receptors (TAARs) to elicit both intraspecific and interspecific innate behaviors (By similarity). Trace amine-binding causes a conformation change that triggers signaling via G(s)-class of G alpha proteins (GNAL or GNAS) (By similarity). In mature olfactory sensory neurons, TAAR9 is coupled with GNAL/G(olf)G alpha protein and mediates activation of adenylate cyclase activity to activate cAMP signaling and eventually transmit odorant signals to achieve membrane depolarization (By similarity). In immature olfactory sensory neurons, TAAR9 is coupled with GNAS/G(s) G alpha proteins (By similarity).
Synonyms: TA3; TAR3; TRAR3; TAR9
Tractability: Small molecule: it belongs to a druggable protein family. Antibody: UniProt places it where antibodies can reach, with medium confidence; UniProt predicts a signal peptide or a membrane-spanning region; its Gene Ontology location is reachable by antibodies, with medium confidence.
Target class: Monoamine receptor; Trace amine receptor; Membrane receptor; Family A G protein-coupled receptor; Small molecule receptor (family A GPCR)
Gene: Protein-coding gene on chromosome 6 (132,538,277 to 132,539,336, forward strand). Ensembl gene ENSG00000237110.
Subcellular location: Cell membrane
Pathways (Reactome):
Signal Transduction: Amine ligand-binding receptors; G alpha (s) signalling events
Gene Ontology:
Molecular function: protein binding; G protein-coupled receptor activity; trace-amine receptor activity
Biological process: adenylate cyclase-activating G protein-coupled receptor signaling pathway; G protein-coupled receptor signaling pathway; sensory perception of smell
Cellular component: plasma membrane; membrane
Genetic constraint (gnomAD): Loss-of-function variants: 0 observed, 0.45 expected, observed/expected ratio (o/e) 0, 90% interval 0 to 1.84. That is too few expected variants to judge how well the gene tolerates losing a copy. Missense variants: 453 observed, 424.14 expected, observed/expected ratio (o/e) 1.07, 90% interval 0.99 to 1.15. Synonymous variants: 162 observed, 160.31 expected, observed/expected ratio (o/e) 1.01, 90% interval 0.89 to 1.15.
Homologues: Orthologues: pig TAAR9 (91% identical), mouse Taar9 (87% identical), rabbit TAAR9 (86% identical), rat Taar9 (85% identical), guinea pig TAAR9 (61% identical). Paralogues in human: TAAR6 (68% identical), TAAR8 (67% identical), TAAR5 (43% identical), TAAR1 (41% identical), TAAR2 (36% identical), HRH2 (28% identical), HTR4 (28% identical), HTR1A (27% identical), HTR1D (26% identical), HRH1 (26% identical), CHRM4 (25% identical), CHRM5 (25% identical), and 13 more.
Diseases named in the same sentence as TAAR9 in open-access papers:
TAAR9 is named in the same sentence as 28 diseases in open-access papers, as found by Europe PMC text mining. Sharing a sentence is not in itself a finding about the gene and the disease. The quoted sentences say what the papers report.
breast carcinoma (3 papers, 2019 to 2025). "This co-expression between genes in primary tumors and metastatic lesions suggests that TAAR9 may play a role in modulating breast cancer progression." (PMID 39944883, 2025). "Indeed, higher expression of TAAR1, TAAR2, TAAR4, TAAR5, TAAR8 (in ER- cases) and TAAR9 provided better survival in breast cancer." (PMID 30718646, 2019).
melanoma (2 papers, 2022). A malignant, usually aggressive tumor composed of atypical, neoplastic melanocytes. "Mutated TAAR9 was identified as a tumor neo-antigen in murine melanoma cells." (PMID 35053262, 2022). "In this study, TAAR6, TAAR8, and TAAR9 expression was found in melanoma samples." (PMID 35053262, 2022). "However, TAAR6, TAAR8, and TAAR9 were still expressed in melanoma." (PMID 35053262, 2022). "TAAR8, TAAR9, DRD1, DRD2, and DRD5 expression was also slightly upregulated in melanomas after immunotherapy (Padj < 0.05)." (PMID 35053262, 2022). "Differential expression analysis demonstrated the drastic decrease of TAAR1, TAAR2, TAAR5, TAAR6, and TAAR8 expression in melanomas compared to benign nevi with only TAAR6, TAAR8, and TAAR9 remaining detectable in malignant tumors." (PMID 35053262, 2022). "In contrast, TAAR6, TAAR8, and TAAR9 were expressed in 12.7%, 11.3%, and 5.3% of tumor specimens, respectively, so their expression is comparable with DRD2, of which expression and activity are well established in melanoma." (PMID 35053262, 2022).
asthma (1 paper, 2022). "It is found that the AUC values of SERPINB2, SLC4A1, TAAR9 in patients with asthma and normal people are 0.854, 0.819 and 0.688, respectively." (PMID 35967302, 2022). "PCR analysis of SERPINB2, SLC4A1, and TAAR9 genes, which also exist in the mouse model of asthma, was conducted to verify the accuracy of the results." (PMID 35967302, 2022).
atherosclerosis (1 paper, 2021). A disease characterized by the build-up of fatty material and calcium deposition in the arterial wall resulting in partial or complete occlusion of the arterial lumen. "In conclusion, our observations suggest that future medications based on TAAR9 antagonism may have potential in the treatments of disorders related to elevated cholesterol levels such as atherosclerosis." (PMID 33799339, 2021). "Importantly, TC-to-HDLC ratio, the main predictive factor of atherosclerosis in human, was decreased in TAAR9-KO rats, but significance was observed only in TAAR9-KOinsA strain." (PMID 33799339, 2021). "Such role of TAAR9 in cholesterol regulation not only brings a new understanding of mechanisms and biological pathways of lipid exchange but also provides a new potential drug target for disorders involving cholesterol-related pathology, such as atherosclerosis." (PMID 33799339, 2021).
coronary disease (1 paper, 2021). "The ratio of triglycerides to HDL-cholesterol (TG/HDLC), an indicator of coronary disease, was not altered in TAAR9 knockout rats." (PMID 33799339, 2021).
Spherocytosis (1 paper, 2021). The presence of erythrocytes that are sphere-shaped. "From these results, we conclude that the lack of the TAAR9 gene is not causing prominent spherocytosis pathology on the stage of differentiated erythrocytes." (PMID 33799339, 2021).
cancer (6 papers, 2018 to 2025). A tumor composed of atypical neoplastic, often pleomorphic cells that invade other tissues. "TAAR1 and TAAR9 were also detected in cancer-associated fibroblasts (CAF)." (PMID 35053262, 2022). "We estimated TAARs’ (including TAAR1, TAAR2, TAAR5, TAAR6, TAAR8, and TAAR9) associations with BC stage, grade, and molecular subtypes in these data and identified that the expression of all TAARs was associated with more unfavorable cancer subtypes, including basal-like and HER2-positive tumors." (PMID 37759760, 2023). "In our study, we selected six human olfactory receptors including OR51E2, OR52cs, TAAR9, OR51E1, OR1A1, and OR1A2 that have been linked with research for the possible development of cancer treatment and detection methods." (PMID 39944883, 2025). "RNAseq data from 12 published cancer studies obtained from cBioPortal detected RNA for TAAR1, TAAR2, TAAR5, TAAR6, TAAR8, and TAAR9 in various cancers." (PMID 29997511, 2018).
neoplasm (2 papers, 2022 to 2023). A benign or malignant tissue growth resulting from uncontrolled cell proliferation. "The overlap between genes co-expressed with TAARs in primary tumors and metastatic lesions is significant, and we found correlations between the expression levels of TAAR1, TAAR2, TAAR5, TAAR8, and TAAR9 and genes associated with neuroactive ligand signaling in both kinds of neoplasms." (PMID 37759760, 2023). "Other TAARs, i.e., TAAR1, TAAR6, and TAAR9, are expressed in the neoplastic epithelium and tumor stroma at the same levels." (PMID 37759760, 2023).
TAAR9 also shares sentences with these, for which no sentence is quoted: chronic fatigue syndrome (1 paper); ciliopathy (1); colon cancer (1); colorectal cancer (1); cutaneous T-cell lymphoma (1); cystic kidneys (1); generalized epilepsy (1); Jeune asphyxiating thoracic dystrophy (1); Joubert syndrome (1); liver cancer (1); lung carcinoma (1); male infertility (1); Obesity (1); osteosarcoma (1); panic disorder (1); personality disorder (1); Pseudoxanthoma elasticum (1); renal carcinoma (1); Retinal dystrophy (1); Sezary syndrome (1).